IL6 (interleukin 6)
Diseases named in the same sentence as IL6 in open-access papers (continued):
Sharing a sentence is not in itself a finding about the gene and the disease.
tumor (continued). "Importantly, HYP-PDT modulated cytokine secretion, significantly decreasing IL-6 and IL-8 levels while increasing TNF-α, suggesting a shift toward a pro-inflammatory microenvironment that could enhance anti-tumor immune responses." (PMID 41226910, 2025). "Notably, effective concentrations (10–20 μM) suppress IL-6 with low-to-moderate cytotoxicity, indicating selective disruption of a tumor-promoting cytokine circuit rather than nonspecific growth inhibition." (PMID 41373438, 2025). "They accomplish this through the increased expression of IL‐6 and CXCL8, which support M2 macrophage polarization, and TGF‐β, which facilitates the recruitment and retention of macrophages in the TME and enables effective tumor evasion of the host immune system." (PMID 39928309, 2025). "Therefore, we hypothesize that once microglia adopt the M2-polarized phenotype, IL6 and CCL2 in the tumor microenvironment are mainly secreted from microglia." (PMID 40444044, 2025). "Similarly, PERK inhibition markedly suppresses tumor growth and angiogenesis in an orthotopic squamous cell carcinoma model by reducing the expression of FGF2, VEGF, and IL‐6, while increasing the levels of antiangiogenic cytokines/chemokines such as thrombospondin 1 (THBS1), CXCL14, and CXCL10." (PMID 40547943, 2025). "SASP factors IL‐6 and IL‐8 are important drivers of cancer proliferation via creating a chronic inflammatory microenvironment, facilitating ECM cleavage by MMPs, and driving epithelial‐to‐mesenchymal transition (EMT), thereby collectively contributing to tumor invasiveness." (PMID 39811803, 2025). "It regulates several genes involved in the functions of the immune system, influences the phagocytic and tumor cell cytotoxic activity of macrophages and reduces the production of different proinflammatory cytokines, such as tumor necrosis factor alpha (TNF-α) and interleukin 6 (IL-6)." (PMID 41516276, 2025). "lncRNA enhancing IL-6/STAT3 signaling activation (LEISA) recruits transcription factor STAT3 to the IL-6 promoter, establishing a feedforward loop that augments IL-6 secretion and STAT3 phosphorylation to promote tumor proliferation and chemotherapy resistance." (PMID 41409273, 2025). "Furthermore, adiponectin reduces the discharge of pro-inflammatory factors (e.g., IL-6 and Monocyte Chemoattractant Protein-1 (MCP-1)) by inhibiting the NF-κB pathway, thereby blocking M2 polarization of TAMs and maintaining an anti-tumor immune microenvironment." (PMID 41164182, 2025). "The NF-kB/IL-6/STAT3 cascade may also be useful to explain the anticancer activity of auranofin, as NF-kB, IL-6, and STAT3 are central players linking chronic inflammation to cancer by driving tumor initiation and subsequent growth and metastasis." (PMID 40333653, 2025). "Multiple lines of transcriptomic evidence in tumor-educated THP1 cells point to STAT3 pathway activation, including upregulation of canonical STAT3 targets (SOCS3, CISH, BCL3, JUNB, PIM1) and increased expression of STAT3-activating ligands (IL6, IL11, LIF, OSM) in response to TNBC contact." (PMID 41514627, 2025). "In this context, IL-6 detection has been demonstrated in point-of-care (POC) platforms for early disease (e.g., sepsis, cancer) diagnosis and prognosis, as well as in OoC models for monitoring inflammatory processes including tumor progression and therapeutic resistance." (PMID 40731649, 2025). "However, several cancer-specific investigations observed an in vitro tumour microenvironment phenomenon where DC2s shifted towards a DC3 like-phenotype, acquiring CD14 and CD163 expression, in response to tumour-derived factors including IL-6 and M-CSF." (PMID 39861894, 2025). "Rather than suggesting a tumour-specific effect, this observation may underscore the pleiotropic and systemic functions of IL-6 in inflammation." (PMID 41465261, 2025).
tumor (continued). "Third, IL-6 impacts the anti-tumor immune response in HNSCC; it regulates the recruitment of immune cells like myeloid-derived suppressor cells and regulatory T cells, which suppress effector immune cells, such as cytotoxic T cells and NK cells, leading to immune evasion by the tumor." (PMID 38534979, 2024). "The enrichment of IL-6/JAK-STAT3 and IL-2/STAT5 signaling pathways in low SIGLEC9 expression suggests that lower SIGLEC9 levels may activate pro-inflammatory pathways that support an anti-tumor immune response by enhancing cytotoxic T cell activity." (PMID 39727942, 2024). "However, after tumor resection, no remarkable changes in cytokine levels were observed in these patients, with the IL-6 level in the After group still higher than that of Control group (p < 0.05)." (PMID 38970045, 2024). "As such, high IL-6 levels are not predictive of tumour chemosensitivity and behaviour in HIV-DLBCL." (PMID 38633747, 2024). "In vitro, Juz- or Gem/Juz-treated KPC tumor cells secreted significantly more macrophage-chemoattractant cytokines, e.g., CCL2, CCL20, and CXCL2, whilst Juz- and Gem/Juz-treated macrophages (MH-S) secreted cytokines of the M1 phenotype, e.g., IL6, TNF-α, and IL12." (PMID 39723364, 2024). "These cells secrete certain proinflammatory cytokines, including interleukin-6 (IL-6), IL-12, IL-1β and TNF-α, and produce inflammatory mediators, such as nitric oxide (NO) and reactive oxygen species (ROS), to activate antitumor immunity at the early stages of tumor onset." (PMID 38409249, 2024). "Local administration of IL-6 to stimulate Tfh cells in the lymph node could reverse the tumor-tolerant microenvironment in the D11 TDLN and recover its antitumor immunity, while direct effects of IL-6 on the primary tumor were ruled out." (PMID 38559676, 2024). "Exposure to either tumor or tumor-adjacent cells, but not to healthy colon epithelium, induced PMN activation and significantly upregulated genes encoding proinflammatory cytokines (Osm, Il6, and Tnf)." (PMID 38329810, 2024). "Analysis of DB7 BCBM tumor lysates using a murine bio-plex cytokine panel showed that rHSVQ treatment induced secretion of chemokines attracting Ly6G + neutrophils/PMN-MDSCs, such as CXCL1, GM-CSF, IL-6, IL-10 and MCP1, which was significantly reduced by oHSV-D11mt treatment." (PMID 38853689, 2024). "Upon entering the tumour microenvironment (TME), the recruited monocytes encounter a wide array of physical (e.g., hypoxia and ECM proteins), chemical (e.g., cytokines (e.g., IL-6), and metabolic (e.g., lactic acid, adenosine, and arginine)) factors known to influence monocyte/macrophage phenotypes." (PMID 39684877, 2024). "The results showed that ATL-1 could reduce the production of extracellular vesicles (EVs) and IL-6 secretion by regulating the STAT3/PKM2/SNAP23 pathway, which inhibited aerobic glycolysis and suppressed the ability of tumor cells to induce muscle atrophy, thus alleviating malignant disease." (PMID 38957318, 2024). "Additionally, IL6 promotes the conversion of non-stem cancer cells into cancer stem-like cells, an inducible model of breast oncogenesis." (PMID 37979099, 2024). "Thus, IL-6 is not required for primary tumor growth or for early cancer cell dissemination to the lungs." (PMID 38645169, 2024). "This suggests that the increased requirement for STAT3 signaling in tumor cells of KPT tumors, including the possible involvement of tumor cells that hitherto did not respond to IL-11, appears to be realized by the coordinated upregulation of IL-6 and its cognate IL-6Ra receptor subunit." (PMID 39128004, 2024). "KD did not affect the size of the tumour or plasma IL‐6 levels." (PMID 38632714, 2024). "Our co-culture investigations, on the other hand, indicated that Jagged2 induces the production and secretion of IL-6 from mesothelial cells via activation of the Notch signaling pathway, imparting mesothelial cell-dependent CSC growth and proliferation advantage to omental metastatic tumor cells." (PMID 38575576, 2024).
tumor (continued). "However, IL-6 and IL-17 expression was also increased in DLN containing collagen matrices with EMT6 tumor cells, yet in this case we saw decreased tumor invasion, despite prior in vivo evidence that IL-6/Il-17 played a role in the enhanced metastasis of EMT6 cells in vivo." (PMID 38540350, 2024). "Furthermore, the absence of evaluations for IL-6 and tumor-infiltrating T cells in the TME indicates that further research is necessary to explore the immunosuppressive effects exerted by IL-6 in a paracrine manner within the tumor tissue." (PMID 38672257, 2024). "In SA region, the expression of IL-6, gp130, and JAK2 was lower in tumor tissues in IL-6+gp130+, IL-6+JAK2+, and IL-6+gp130+JAK2+ cells (P < 0.05); and the expression of IL-6R, CRP was also lower in tumor tissues in IL-6R+CRP+, IL-6R+STAT3+, and IL-6R+CRP+STAT3+cells (P < 0.05)." (PMID 38881895, 2024). "Also, studies found that cancer cell-derived exosomal miRNAs can bind to TLRs in macrophages and intestinal cells and stimulate NF-κB pathway with subsequent release of the pro-inflammatory and pro-metastatic cytokines IL-6 and TNF-α which stimulate tumor growth and metastasis." (PMID 38987740, 2024). "Previous studies have shown that IL6 could regulate cell fate and promote cancer cell growth through the STAT3 signaling pathway, whereas Gremlin 1 could maintain cell stemness and promote tumor growth." (PMID 39872866, 2024). "Finally, we assessed whether Yap1-depletion in Yap1KD; Gp130FF tumor organoids reduced expression of gp130 cytokines and found that indeed this effect was more pronounced on IL11 than IL6." (PMID 37957015, 2024). "Since both IL-6 and IL-8 were shown to positively impact tumor propagation by enhancing immune evasion, angiogenesis, and metastatic potential, our findings indicate that both low- and high-LET radiation can augment the tumor-promoting attributes of chronic hypoxia." (PMID 38674080, 2024). "In addition, some physicians have expressed concerns regarding the potential of IL-6 inhibition to induce tumor hyperprogression; however, there is no clear evidence to support this view." (PMID 39703501, 2024). "Intermittent “spikes” in catecholamines and other acute exercise factors, such as the muscle-derived cytokines IL6 and IL15, can recruit effector lymphocytes to the blood and facilitate their trafficking to tumors leading to enhanced tumor infiltration and suppression of tumor growth over time." (PMID 38592213, 2024). "Importantly, the gp130 inhibitor could effectively reverse the tumor-promoting effects of M-BMDMs via IL-6/STAT3 signaling blockage, pointing to its potential therapeutic usage for tumor treatment." (PMID 38274367, 2024). "For instance, TAM derived cytokines, such as IL‐6, IL‐1β, IL‐8, TNF‐α, CCL‐17, and CCL‐22 significantly contribute to proliferation of GC cells, immunosuppression and angiogenesis in TME through the mediation of immune surveillance which support tumor growth and metastasis as a result." (PMID 38349050, 2024). "The negative prognostic role of IL-6 for ICIs has already emerged in other tumor subtypes." (PMID 38799450, 2024). "In Phase II clinical trials (MHRA 21313/0007), Siltuximab showed significant reductions in IL6, CCL2, CXCL12, and VEGF levels, leading to decreased angiogenesis and macrophage infiltration, further validating the potential of Siltuximab in altering the tumor microenvironment." (PMID 39766086, 2024). "Additionally, we investigate the downstream effectors of TOP1 in CC cells and identify TOP1-mediated tumor-promoting inflammatory features, characterized by alterations in the expression of CXCLs, HMGB1, IL-6, and STAT3/5, as well as several T cell regulatory genes." (PMID 39156107, 2024). "Tumor markers including alpha-fetoprotein (AFP), human chorionic gonadotropin (hCG), and carcinoembryonic antigen (CEA), as well as inflammatory markers such as C-reactive protein (CRP), procalcitonin (PCT), and interleukin-6 (IL-6), were all within normal ranges." (PMID 38600577, 2024).
tumor (continued). "Thus, we analyzed the secretory factors in cultures of astrocytes and tumor cells and cocultures of these cells and found increased abundances of various soluble factors, such as MIF, CCL2, IL-6, and IL-8, primarily in astrocyte cultures compared to cultures of the other cell types." (PMID 38825648, 2024). "However, PPAR-γ agonists did not affect tumorigenesis in the Aqp3 knockout mice, but IL-6 secretion increased the number of nodules and tumor proliferation." (PMID 39060229, 2024). "Furthermore, a correlation between IL-6 and pathological factors such as the presence or absence of bone invasion, tumor invasion depth, and vascular invasion has been reported." (PMID 38510850, 2024). "Overactivation of the IL-6 pathway may weaken the Th1 response and hinder T cell recruitment in the lymph nodes and the tumor microenvironment (TME), consequently suppressing anti-tumor T cell immunity." (PMID 38304429, 2024). "Fibroblast-like changes in CAAs are accompanied by the downregulation of terminal differentiation markers and the upregulation of pro-inflammatory cytokines (IL-6 and PLOD2), ultimately leading to the emergence of adipocyte-derived fibroblasts that may incorporate tumor stromal components 131-133." (PMID 38481820, 2024). "IL-6 is an inflammatory cytokine and low-molecular-weight glycoprotein secreted by lymphocytes (T cells and B cells) and non-lymphocytes (monocytes, dendritic cells, and tumor cells)." (PMID 39881879, 2024). "Beyond its generic tumor-promoting effects, the IL-6 axis could make unique contributions specifically to PC as a unique metastatic pattern, irrespective of primary tumor site." (PMID 38689325, 2024). "However, when miR-9 and miR-218 downregulated the expression of IL-6 and Janus kinase 2 (JAK2), they inhibited the activation of STAT3, leading to the downregulation of STAT3 expression and thus inhibiting the growth of tumor cells." (PMID 38172648, 2024). "In this current systematic review, patient level data for IL-6 inhibition was limited such that the impact on tumor outcome could not be rigorously assessed." (PMID 39737191, 2024). "The results of this study suggest that MZLAE may have a preventive effect on tumour initiation by reducing dysplasia development, as well as decreasing ROS, superoxide production, and inflammation through the downregulation of TNF-α and IL-6 proteins." (PMID 39290583, 2024). "Therefore, when considering the notably low (IL‐6 and IL‐27) and high (IL‐10) level of cytokines, as well as lower number of CD163+ cells, 2‐ME may also have rendered an anti‐tumor effects such as the greater tumor necrosis." (PMID 38600057, 2024). "Moreover, other cytokines such as IL‐6, IL‐1β, VEGF, and IL‐10 have been correlated with poor prognosis in cancer patients due to their role in regulating myeloid cell (e.g., MDSCs) differentiation and recruitment to the tumor." (PMID 37681284, 2024). "Additionally, MSCs indirectly support tumour vasculature by secreting pro-angiogenic factors, including VEGF and other pro-angiogenic cytokines, such as fibroblast growth factor (FGF), ANGPT-1, and IL-6, which are necessary for the angiogenic activity of VEGF." (PMID 39200142, 2024). "IL-6 and IL-8 might in turn stimulate ATX expression in ADSC in the tumor microenvironment." (PMID 39338222, 2024). "In addition, hypoxia induces HMGB1 expression in mouse and human HCC cells in a HIF-1α-dependent manner, driving TAM recruitment and polarisation and elevating IL-6 concentrations, which further exacerbates EMT, vascular invasion, and the metastasis of HCC tumours." (PMID 39684877, 2024). "Tumor cells trigger the coagulation cascade via the tissue factor (TF) and the induction of proinflammatory cytokines, such as tumor necrosis factor alpha (TNF-a), interleukin 1 (IL-1), interleukin 6 (IL-6), interleukin 8 (IL-8), and transforming growth factor beta (TGF-b)." (PMID 39063619, 2024).
tumor (continued). "Stimulation of MDSCs in cancer patients is mostly driven by tumour-derived growth factors such as granulocyte-macrophage colony-stimulating factor (GM-CSF), granulocyte colony-stimulating factor (G-CSF), macrophage colony-stimulating factor (M-CSF), VEGF, and IL-6." (PMID 38920685, 2024). "Moreover, IL-6 released in the TME also suppresses the differentiation of IFN-γ-producing TH cells by attenuating both surface expression of MHC-II and secretion of IL-12 in dendritic cells of tumor-bearing mice, in a STAT3-dependent manner." (PMID 39281678, 2024). "The ability of IL‐6 to initiate ferroptosis is equally striking, which can disrupt intracellular iron homeostasis via JAK/STAT3 while using protein kinase (ERK) as a signalling amplifier inhibition of the antioxidant function of the xc‐system catalyses ferroptosis in tumour cells." (PMID 38652105, 2024). "By interacting with IL-6 receptor (IL-6R), IL-6 activates STAT3 by upregulating the expression of cyclin D1, D2, and B1, and c-Myc and downregulating the expression of the cyclin-dependent kinase (CDK) inhibitor p21, which collectively accelerates the entry of tumor cells into cell cycles." (PMID 38520006, 2024). "The signal values of IL-6 in tumor tissues were low, regardless of serum IL-6 levels." (PMID 38510850, 2024). "Compelling evidence suggests that IL-6 derived from CAFs mediates therapeutic resistance, including chemoresistance by upregulating CXCR7 expression via STAT3/NF-κb pathway in ESCC, and IL-6 blockade improves checkpoint blockade therapy and promotes tumor immunity." (PMID 39334513, 2024). "Factors like hypoxia, heterogeneous blood supply, and the presence of various cytokines (IL-1, IL-6, TNF-α, and IFN-γ) and enzymes can affect the activity or expression level of the therapeutic enzyme cytochrome P450, the distribution of the prodrug and its metabolites within the tumor." (PMID 38860140, 2024). "These neuroendocrine mediators elevate inflammatory cytokines (e.g., IL-6, IL-8) and immunosuppressive cytokines (e.g., IL-4, IL-10, VEGF), suppressing NK cell and Tc cell activity while promoting regulatory T (Treg) cell expansion, ultimately contributing to tumor progression." (PMID 39597826, 2024). "Moreover, HIS treatment reversed the elevated serum levels of inflammatory factors (IL-6 and IL-17A), stress hormones (NE and COR), and 5-HT, all of which have been shown to be upregulated under chronic stress and promote tumor progression, consistent with previous research." (PMID 39720595, 2024). "Although IL‐6 was clearly expressed by the tumour, its mRNA level was not blunted by AdipoRon." (PMID 38572511, 2024). "In addition, there was no change in tumour gene expression of proinflammatory cytokines (Tnfa, Il1b, Il6 and Osm) between untreated and AR‐treated C26 mice." (PMID 38572511, 2024). "Additionally, ketamine decreases pro-inflammatory cytokines, such as IL-6 and TNF-α, which may further inhibit tumor growth." (PMID 39597826, 2024). "Our study found a significant decrease in IL-6, IL-1β, IL-17A, and TNF-α levels in mice after L.p CMU-Pb-L5 intervention, indicating that L.p CMU-Pb-L5 intervention could reduce inflammatory cytokine levels in vivo and slow CRC tumor growth." (PMID 39439459, 2024). "Additionally, IL-6 itself has been found to increase hypermethylation of SOCS3, all of which may contribute to a positive feedback loop in the H. pylori-infected tumor microenvironment." (PMID 38422751, 2024). "In this model, senescent mouse fibroblasts displayed elevated secretion of the canonical SASP factor, interleukin-6 (IL-6), and co-injection of senescent fibroblasts led to an increase in Ras-induced tumour growth, suggesting that non-malignant senescent stromal cells can drive tumour development." (PMID 39277623, 2024).